FGF2 (fibroblast growth factor 2)
Diseases named in the same sentence as FGF2 in open-access papers (continued):
Sharing a sentence is not in itself a finding about the gene and the disease.
tumor (continued). "So, we speculated that miR-877-3p might exert its tumor suppression role by interacting with FGF2." (PMID 34738872, 2022). "In tumor-bearing mice, serum FGF2 increased steadily from baseline levels (11.84 ± 10.70 pg/mL) to the peak (104.72 ± 16.55 pg/mL) within 3 weeks after tumor implantation (P < 0.001), and declined immediately after tumor removal, confirming that serum FGF2 was mainly secreted by ESCC cells." (PMID 35941662, 2022). "Thus, the impact of the rs1048201 SNP on a long-term endpoint such as OS, found in the combination treatment group, could be supported by the direct effect of FGF2 on tumor survival and metastasis." (PMID 35406617, 2022). "In addition, the higher expression of fibroblast growth factor 2 (FGF2) and CD14 can be associated to the great ability of WT spheroids to influence the other cellular components of tumor microenvironment, such as fibroblasts and monocytes positively supporting tumor development." (PMID 36230687, 2022). "The ability of macrophage GAG species to present FGF-2 might promote tumor cell proliferation." (PMID 35954218, 2022). "However, the spatiotemporal expression of FGF-2 in the tumor microenvironment is unclear." (PMID 35985991, 2022). "The results of the two groups suggest that TGF-β and FGF2 oppose and cooperate with each other during the formation of myofibroblastic and non-myofibroblastic cells from TECs, determining the characteristics of EC-derived mesenchymal cells in the tumor microenvironment." (PMID 35130955, 2022). "To test that hypothesis, we treated various cells with FGF-2 and cocultured them with tumor cells." (PMID 35439170, 2022). "Thus, targeting FGF-2 was considered to be a promising anti-tumor strategy." (PMID 33718141, 2021). "Therefore, stiffness-E2F3 promoted HSCs to generate and release tumor-promoting factors, FGF2." (PMID 34873170, 2021). "Additionally, FGF-2 strongly stimulates the proliferation and migration of tumor cells." (PMID 33718141, 2021). "Conversely, studies have also shown that FGF2 may suppress tumor growth." (PMID 35002617, 2021). "As no change of potential angiogenic genes (Fgf2, Vegfa) nor inducible nitric oxygenase (Nos2) was observed, we proposed that the vasodilation was caused by AuNP-dependent decomposition of nitrosothiols and direct release of nitric oxide in the tumor tissue." (PMID 33653008, 2021). "FGF-2 could promote tumor proliferation, migration, and angiogenesis as a key angiogenic factor." (PMID 33718141, 2021). "In addition, FGF2 can be an activator of angiogenesis during tumor mass growth and metastasis." (PMID 34201896, 2021). "We asked whether the FGF2 blocking antibody led to effects on tumour vascularity." (PMID 32792542, 2020). "However, further validation is required to establish whether the upregulation of FGF2 and Runx2 is linked to BMP2 expression in EBV-associated NPC and other virus-associated tumours." (PMID 32708289, 2020). "It was reported that FGF2 inhibition or FGF2/FGFR signaling pathway may reduce tumor progression." (PMID 32370284, 2020). "Thus macrophages were the main immune cell subtype within tumours that might be expected to respond directly to FGF2." (PMID 32792542, 2020). "Indeed, PDGF and FGF2 was unable to rescue the growth of tumor OPCs after IGF1R was knocked down." (PMID 33173731, 2020). "Therefore, there might be spatially effective activation of the FGF2 signaling pathway between endothelial cells and pericytes in tumor vasculatures that are resistant to anti-VEGF therapy." (PMID 32076044, 2020). "FGF2 has not previously been implicated in the regulation of macrophages, nor in tumour immunity." (PMID 32792542, 2020). "Moreover, FGF2 overexpression promotes tumor growth and progression." (PMID 32370284, 2020).
tumor (continued). "Specifically, FGF2 is the main member of the FGF family implicated in cancer development and drug resistance, and PDGFD and its receptor (PDGFRB) have been recently defined as key drivers of tumor progression since a PDGFRB downregulation impairs immediately GBM progression (A.C.V.-B." (PMID 34316686, 2020). "Increased activity of autocrine/paracrine loops in tumor cells might also be important in tumor pathogenesis due to the well-known abilities of FGFs, and especially FGF2, to stimulate angiogenesis and thus promote tumor growth, invasion and disease progression." (PMID 31948066, 2020). "Furthermore, we investigated whether the treatment with FGF2-SPIONs also leads to the inhibition of tumor stroma by attenuating the activation of hPSCs." (PMID 31911892, 2020). "Hence, inhibition of FGF2 delays tumor growth via normalizing the vasculature." (PMID 31474975, 2019). "Interestingly, this accumulation of FGF-2 may be relevant to cancer cells in metastatic microenvironments, where it may contribute to a dormant state of tumor cells." (PMID 31717665, 2019). "PSS itself has no inhibitory effect on the growth of B16-F10 cells—however, it suppressed FGF2-mediated angiogenesis and invasion of B16-F10 cells, and also decreased the level of Vimentin, which might help enhance the sensitivity of tumor cells to chemotherapy." (PMID 31035725, 2019). "Given the role of FGF2 in the maintenance of cancer stem-like cells, the loss of stem-like traits in PTX3 overexpressing BC cells might be the result of the FGF trap action of PTX3, with a possible significant impact on different tumor features." (PMID 31480336, 2019). "In particular, resveratrol affects tumor angiogenesis by inhibiting endothelial cell migration, proliferation and new blood vessel formation through the inhibition of fibroblast growth factor 2 (FGF2) and VEGF receptor-mediated activation of MAPK in endothelial cells." (PMID 31370258, 2019). "Finally, we demonstrated that PROX1 and other vascular factors, such as VEGFC (vascular endothelial growth factor C), BAIAP2 (BAI1 associated protein 2), FGF2 (fibroblast growth factor 2), and PLAT (plasminogen activator) are differently expressed in FTC human tissues compared to non-tumor tissues." (PMID 31717665, 2019). "In addition, FGF-2 significantly stimulated tumor angiogenesis." (PMID 29423271, 2018). "Interestingly, FGF2 blocks Shh signaling in neuronal precursors and tumor cells." (PMID 29662197, 2018). "Besides, we also showed that a chemotherapeutic drug such as DOX could affect tumor angiogenesis by modulating the expression of the angiogenic factor FGF-2." (PMID 30564299, 2018). "Thus, our findings that KO/PyMT tumour cells are deficient in proliferative responses to HSPG-dependent (FGF2), but not HSPG-independent (EGF) growth factors are consistent with the possibility that α3(V) chains aid GPC1 co-receptor function." (PMID 28102194, 2017). "Taken together with the results from mouse models, these findings indicated that fibrocytes may be one of the key regulatory cells in the tumor microenvironment that are involved in the acquisition of resistance to anti-VEGF therapy through their production of FGF2." (PMID 29286323, 2017). "In addition, we suggest that the effect of HET0016 on tumor growth may be attributed to the reduced basic fibroblast growth factor expression (bFGF or FGF-2) after early and delayed treatment." (PMID 28139732, 2017). "The A2AR agonist CGS21680 did not induce CXCL12 or FGF2 expression in tumor associated fibroblasts." (PMID 27590504, 2016). "Furthermore, NEP cleavage of angiotensin, bradykinin and fibroblast growth factor-2,4, 45 all important regulators of angiogenesis, suggests that it could be a regulator of tumor angiogenesis." (PMID 26950599, 2016). "Therefore, FGF2 may contribute to cancer progression through alternative mechanisms involve acting directly on tumor cells." (PMID 27007053, 2016).
tumor (continued). "With regard to the cells responsible for producing FGF2 in the resistant tumours, the results from our study demonstrated that fibrocyte-like cells may be a major source, in addition to macrophages and the tumour cells themselves." (PMID 26635184, 2015). "The role of inflammasomes in carcinogenesis is contrasting; they may inhibit tumor promotion by activating caspase-1 and cell killing, or may promote tumor growth by upregulating secretion of pro-inflammatory molecules like, IL-1β, IL-18, FGF2 and HMGB1." (PMID 26689911, 2015). "Thus, ARPCA may act as a FGF2/FGF8b antagonist able to affect tumor epithelial and stromal compartments by suppressing the autocrine/paracrine action of both growth factors." (PMID 25912421, 2015). "Accordingly, in vitro studies have shown that tumor-derived TGFβ is able to induce activation of human prostate stroma through heavy deregulation of key signalling pathways crucially involved in maintaining tumor-promoting features, including FGF2, CTGF, SDF1, WNT3A and IGF axes." (PMID 26375444, 2015). "The tumor growth promotion is supported by the fully glycanated endocan through two main mechanisms requiring the presence of a glycan chain: a comitogenic property with several growth factors like FGF-2 or HGF/SF, and a chemokinetic property on endothelial cells." (PMID 25575808, 2015). "Interestingly, tumor-derived SCF has been recently implicated both in MCs recruitment into the tumor environment as well as in increased MCs release and production of VEGF and FGF-2." (PMID 25295247, 2014). "In addition, FGF2 could function as a growth factor on the tumor cells in a paracrine/autocrine fashion, activating intracellular pathways and ultimately leading cells to proliferate, avoid apoptosis or become insensitive to antigrowth signals." (PMID 21733164, 2011). "Furthermore due to the emerging role of FGF-2 in tumour angiogenesis and its potential role in drug resistance to anti-angiogenic agents, understanding the FGF-dependent signalling pathways will prove useful to design novel potential strategies of intervention." (PMID 20011604, 2009). "Alternatively, FGF2 may be released under hypoxic stress as a potent angiogenic factor; it may affect bone remodelling and thus tumour progression by osteoclast recruitment, or it may act in a paracrine fashion by inducing growth factor production in bone marrow stroma cells." (PMID 15685229, 2005). "Additionally, at the end of the 7 day treatment period, clonogenic excision assays showed that the percentage of hypoxic cells in tumours from mice receiving FGF-2 administration was significantly decreased as compared to control neoplasms (from about 42 to about 19%)." (PMID 8398700, 1993). "Tumor angiogenesis and vascular remodeling occur through the contribution of VEGF, FGF-2, and PDGF growth factors." (PMID 41514933, 2026). "We observed that about one-fifth of ER+ tumor samples were positive for FGF2 expression both epithelial and mesenchymal, whereas over 80% of TNBC samples were positive for FGF2." (PMID 40425576, 2025). "A study reported that AZD4547 significantly retarded tumor growth by inducing the mesenchymal–epithelial transition (EMT), reducing ESCC stem cell-like cell populations (CSCs), and inhibiting FGF2-mediated FGFR/ERK signaling." (PMID 40722739, 2025). "In CRC, IL-8 is secreted by TAMs and cancer cells and promotes tumor angiogenesis and pre-metastatic microenvironment formation by inducing the expression of VEGF and FGF2." (PMID 40109347, 2025). "The content of several angiogenic and proinflammatory factors, including VEGFA and FGF2, was reduced in other SHP2-silenced tumor cells from culture and the tumors they generated." (PMID 40131370, 2025). "In gastric cancer, CAF-derived IGFBP7 enhances the FGF2/FGFR1–PI3K/AKT pathway, promoting TAM recruitment and polarization, thereby establishing a pro-tumorigenic CAF–TAM–tumor cell axis." (PMID 41514604, 2025).
tumor (continued). "Fibroblast growth factors (FGFs), particularly FGF2, are known for their roles in angiogenesis and tissue repair, with dysregulated FGF signaling contributing to tumor growth, survival, and angiogenesis." (PMID 39833941, 2025). "N2 neutrophils facilitate tumor angiogenesis by releasing factors such as vascular endothelial growth factor (VEGF) and matrix metalloproteinase-9 (MMP-9), and fibroblast growth factor-2 (FGF-2), ultimately promoting tumor proliferation and metastasis." (PMID 41200171, 2025). "They express proteins like AGR2 to potentiate VEGF and FGF2 signaling, and REG4 to intensify tumor invasion." (PMID 41450739, 2025). "During this process, endothelial cells (ECs) are activated by pro-angiogenic factors released from the tumor microenvironment (TME), such as vascular endothelial growth factor (VEGF) and basic fibroblast growth factor (FGF2)." (PMID 39899169, 2025). "The cell-type-specific (defined based on marker gene expression profiles and clustering analysis) expression of CD44, FGF2, FGF10, KDM6A, FN1, and MMP2 in the tumor microenvironment of UCEC was analyzed using the TISCH2 database." (PMID 39833941, 2025). "In response to tumor hypoxia, HIF-1α is stabilized, resulting in the upregulation of pro-angiogenic factors, including VEGF, PDGF, and FGF-2." (PMID 39057155, 2024). "Reconciling with the effect of FGF2 ablation, treatment with the neutralizing antibody against FGF2 (3F12E7) significantly reduced popliteal lymph node volume and LNMAC‐transduced tumor burden." (PMID 39119899, 2024). "Basic FGF (bFGF, FGF2) is an important ligand of FGFR1 in GBM, and together, they increase self-renewal and maintenance of GBM cancer stem cells, thereby driving tumor growth." (PMID 39682716, 2024). "Elevation of different angiogenic factors, including VEGF, FGF-2, and platelet-derived growth factor (PDGF) in response to tryptase plays a key role in tumor angiogenesis." (PMID 39749033, 2024). "Another family of cytokines that can promote all the events underlying angiogenesis is that of the fibroblast growth factors (FGFs): amidst them, FGF-2, also termed basic FGF, takes on particular importance in tumor angiogenesis." (PMID 39120324, 2024). "SULF1, an extracellular heparan sulfate endosulfatase, regulates key growth factor pathways such as FGF2 and VEGF, impacting angiogenesis and tumor progression." (PMID 39850570, 2024). "We found that exposure to FGF2, FGF18, HBEGF, IGF1, PDGF-BB, and TGFα significantly (p < 0.0001) increased MCL1 expression in tumor cells (by at least 1.2-fold and up to 2-fold) and treatment with the MEKi reduced this response." (PMID 37676378, 2024). "Tumour cells produce angiogenic factors such as VEGF interleukin-8 (IL-8), basic fibroblast growth factor (bFGF/FGF-2), and matrix metalloproteinases (MMPs), which promote the formation of new blood vessels." (PMID 38794316, 2024). "Studies revealed that interplay of the growth factors—VEGF, MMP, and bFGF/FGF-2 promote active angiogenesis and tumor development." (PMID 38213742, 2024). "Thalidomide and lenalidomide combine immunomodulatory and anti-angiogenic effects by inhibiting NF-κB activity, TNF-α expression, and (to a lesser extent) FGF-2 and VEGF expression in various tumor cell types." (PMID 39796700, 2024). "Western blot analysis illustrated that LY2874455 treatment restrained FGF1, FGF2, STAT1, and LDHA levels but increased LDHB levels in tumor tissues." (PMID 38764020, 2024). "B cells enhance EC function in a STAT3-dependent manner by expressing VEGFA, FGF2, and MMP-9, thereby promoting tumor angiogenesis." (PMID 39691707, 2024). "Noticeably, FGF-2 triggers either PI3K/AKT or MAPK/ERK in a wide variety of normal, as well as tumor, cells." (PMID 39120324, 2024). "The exosomal miR-210 derived from tumor cells induces the reprogramming of NFs to CAFs through TET, further promotes tumor angiogenesis and progress by producing MMP9, FGF2 and VEGF." (PMID 38825680, 2024).
tumor (continued). "Our data show that FGFRL1 is expressed in macrophages, and FGF2 has been shown to regulate programming of TAM and to control tumor growth and antitumor immunity." (PMID 38358826, 2024). "As the tumor growth advances, the tumor cells themselves produce growth factors, for example, PDGF, FGF-2, and TGF-β, which activate stellate cells and their production of ECM proteins." (PMID 38891809, 2024). "Conventional FGF1 and unconventional FGF2 interact with FGFR3 and FGFR1 on tumours, respectively, which promotes the enhancement of tumour cell invasion mediated by CAFs." (PMID 40135140, 2024). "PERK-mediated upregulation of vascular endothelial growth factor (VEGF), fibroblast growth factor-2 (FGF2), and interleukin-6 (IL-6), coupled with the downregulation of anti-angiogenic cytokines, markedly promotes tumor growth." (PMID 38673794, 2024). "Like VEGF, FGF-2 upregulates HIF-1 expression in carcinoma cells, thereby potentiating HIF-1 activity and keeping it even when oxygen levels in tumor tissue are normal." (PMID 39120324, 2024). "FGF1 and FGF2 mutants defective in integrin binding were defective in signaling, whereas the mutants still bound to FGFR suppressed angiogenesis and tumor growth, indicating that they act as antagonists." (PMID 38391921, 2024). "These cells produce several angiogenic factors, including fibroblast growth factor-2 (FGF-2), vascular endothelial growth factors (VEGF), and interleukin-8 (IL-8), as well as proteases, promoting tumor neovascularization." (PMID 39749033, 2024). "Different pro-angiogenic factors including VEGF, TGFβ, fibroblast growth factor 2 (FGF-2), IL-6, and IL-8, are present in exosomes derived from tumor cells." (PMID 39035739, 2024). "FGF2 was highly expressed in antiangiogenic drug-resistant NPC, and its knockdown reduced tumour angiogenesis." (PMID 37782406, 2024). "In summary, this study reveals differential activation of salvage angiogenic pathways in surgical specimens, with FGF2, EphA2, and PLGF upregulated in tumor vessels, while ANGPT1 and ANGPT2 were downregulated and upregulated, respectively." (PMID 38619734, 2024). "MDSCs also express FGF-2, PDGF, IL-1β, IL-28/IFN-λ, TGFβ, EGF, and HGF that can stimulate EC proliferation and migration, contributing to tumor angiogenesis." (PMID 38580870, 2024). "For example, MCs release FGF-2, NGF, PDGF, VEGF, IL-8, and IL-10, which promote the expansion of tumor cells." (PMID 38233752, 2024). "Regarding FGF-2, it can directly upregulate uPA expression, while ANG-2 levels positively correlate with those of uPA and uPAR in tumor specimens, as well as during wound healing." (PMID 39120324, 2024). "Other regulators in the TME, such as fibroblast growth factor-2 (FGF2) and the platelet-derived growth factor (PDGF) family, can also participate in the generation of tumor vasculature." (PMID 39408814, 2024). "We also identify a fibroblast growth factor-2 (FGF2) mediated mechanism for DNMT1 regulation, thus linking a potent endothelial cell (EC) mitogen with proliferative yet immunologically anergic tumor vasculature." (PMID 37055433, 2023). "Apart from angiogenesis, the induction of tumor–endothelial adhesion and pulmonary leakiness by vWF‐SAM‐sEVs was also suppressed by anti‐VEGF‐A and anti‐FGF2 antibodies." (PMID 37387563, 2023). "Macrophages can shift functionally from M1 to M2, with M1 macrophages being pro-inflammatory and exerting tumoricidal effects, while M2 macrophages typically promote tumor growth by producing growth factors, including VEGF, FGF2, and TGFβ." (PMID 37371127, 2023). "Conversely, mediators released by mast cells such as FGF-2, NGF, PDGF, VEGF, IL-8, and IL-10 can promote the expansion of tumor cells." (PMID 36793597, 2023). "PPI network analysis revealed these genes and modules were mainly related to tumor progression (LOXL1, IKBKE, LNX1, FOXA2, FGF17, and FGF2) and immune response (STAT4, IL23R, LTA, ITK, and IL19)." (PMID 36611170, 2023).